BCL2 (BCL2 apoptosis regulator)
Diseases named in the same sentence as BCL2 in open-access papers (continued):
Sharing a sentence is not in itself a finding about the gene and the disease.
cancer (continued). "However, cancer cells resist apoptosis by downregulation of Bax and upregulation of Bcl-2." (PMID 35003514, 2021). "These molecules have been shown to reduce off‐target effects in biological experiments; ligand 3ao and 3ap could selectively downregulate the expression of c‐MYC and BCL2 genes, respectively via stabilization of promoter quadruplexes and eventually lead to apoptosis in cancer cells." (PMID 34138492, 2021). "Notably, BCL2L1-gained cancer was even resistant to BCL-2-targeted agents." (PMID 34351305, 2021). "Therefore, Bcl-2 is considered an inhibitor of apoptotic proteins and may be an important target for cancer treatment." (PMID 33833342, 2021). "In addition, understanding the role and function of the Bcl-2 isoforms specifically present in some cancer cells may be useful for selective cell targeting leading to cell eradication as well as modulation of several cell pathways." (PMID 34573088, 2021). "Finally, we clustered the four cell lines based on the overlap of interaction partners for each bait between pairs of cell lines, and observed a clear clustering of cancer cells (G401, T47D, and A375) versus GPiNs for three out of four bait proteins (BCL2, TDP-43, and PTEN)." (PMID 33972534, 2021). "Although speculations regarding the biological function of Bcl-2 phosphorylation have been controversial, it is certain that Bcl-2 phosphorylation at the Ser70 residue is important and frequently occurs in several cancer types following exposure to microtubule-targeting drugs." (PMID 34391437, 2021). "Overexpression of Bcl-2 in cancer cells may block apoptosis and enhance cell survival." (PMID 34174900, 2021). "The role of BCL2, an anti-apoptotic protein, is dependent on the estrogen receptor (ER) status, which may explain the ineffectiveness of Rlip depletion in the PyVT viral cancer model." (PMID 34283045, 2021). "From these three groups, the BAX (pro-apoptotic) and Bcl-2, Bcl-xL or Mcl1 (anti-apoptotic) proteins have gained the most attention over the recent decades, based on their deregulated expression, significance in the development of a number of cancers and their responsiveness to therapeutics." (PMID 34753495, 2021). "Carrageenan mechanism in inhibiting the growth of cancer cells has also been investigated, where carrageenan is able to induce the process of apoptosis through activating the pathways of caspase-3, caspase-8, and caspase-9; remodulation of the Bax:Bcl-2 ratio; and DNA damage." (PMID 34064093, 2021). "Reports on the antiproliferative properties of CGA revealed that it could disrupt the cancer cell cycle and induce apoptosis via increasing the expression of both Bax and caspase-3 genes and decreasing the level of B-cell lymphoma 2 (Bcl-2)." (PMID 34641577, 2021). "In addition, many natural polyphenols induced cancer cell death by downregulating Bcl-2 expression." (PMID 33809701, 2021). "Hence, Bcl-2 protein has been considered an important target for anti-cancer therapeutics." (PMID 34366863, 2021).
cancer (continued). "It is documented that members of the Bcl‐2 family, including Bcl‐2 and Mcl‐1, regulate apoptosis and caspase activation by regulating the mitochondrial membrane integrity, and the decline of the expression levels of Bcl‐2 members contributes to apoptosis induced by some anti‐cancer agents." (PMID 34318593, 2021). "Bcl-2 inhibitors may inhibit cancer cell growth and survival." (PMID 34638779, 2021). "Furthermore, increased H2O2 levels coincide with increased FADD intermembrane translocation and FasL, which activate initiator caspase-8 in the extrinsic apoptotic pathway, whereas decreasing O2•- sensitizes Bcl-2 overexpressing cancer cells to receptor or drug-induced apoptosis." (PMID 34777681, 2021). "The properties of Bcl-2 genetic in dog may help to find the drug designing in cancers." (PMID 34359246, 2021). "Importantly, the epithelial lesions are preceded by enhanced activation of cytoplasmic and nuclear NF-κB promoting significant molecular alterations of cancer-related genes, such as Bcl2, Egfr, Stat3, Tnf, and Il6, and miRNA markers, such as miR-21, miR-155, miR-192, miR-375, miR-451a, and miR-34a." (PMID 32344873, 2020). "Therefore, our results indicated that reduced expression of CD9 and CD81 in HCC may activate JNK signaling pathway, which promotes cancer cell proliferation via regulating the downstream genes such as Cyclin D1 and Bcl-2." (PMID 32350244, 2020). "Therefore, inhibition of Bcl2 and BclxL makes cancer cells more vulnerable to apoptosis." (PMID 32703189, 2020). "Moreover, the obtained data demonstrated that AdE upregulated the level of the proapoptotic protein Bax in HepG2 cancer cells by 9.8 folds compared to the Ctrl while it downregulated the level of the antiapoptotic protein Bcl-2 by 2.7 folds compared to the Ctrl in the same cell line." (PMID 33294124, 2020). "Although the study concerned another anti-apoptotic protein, Bcl-2, it showed that the imbalance between the pro- and anti-apoptotic proteins may significantly increase sensitivity of the examined cancer cells to the cytostatic drugs commonly used in the therapy." (PMID 32260403, 2020). "Thus, the combination of Bcl-xL/Bcl-2 inhibitors and T3 enhanced apoptosis of cancer cells." (PMID 33064779, 2020). "In addition to a highly significant decrease (p = 0.005) in Bcl-2 of cancer cells." (PMID 32372389, 2020). "BCL-2 could facilitate the survival of cells and the pathogenesis of cancer." (PMID 32970954, 2020). "We may hypothesize that the lower expression of IL-6 determined in M. U-care–treated mice would be related to a decrease in cancer cell proliferation, in which IL-6 could act on Bcl-2 expression, altering the proliferation/apoptosis balance toward neoplastic cell apoptosis." (PMID 32423132, 2020). "Therefore, targeting of Bcl-2/IP3R interactions could be a potential therapy in several cancer types including PCa." (PMID 32344908, 2020). "Similarly, Bcl-2 is well-documented as a suppressor of apoptosis in various cancers including OS." (PMID 32972441, 2020). "Moreover, a dry Maytenus ilicifolia extract protects normal cells and induces apoptosis, decreasing BCL-2 in human cancer cells." (PMID 32121436, 2020). "Therefore, chemotherapeutic drugs may provide an additional important event required to empower the Bcl‐2 inhibitor to eliminate resistant cancer cells." (PMID 32346976, 2020). "A subsequent molecular docking study suggested that the insertion of the thio group into the cycloalkane ring and the substitution of a hydrophobic moiety on the phenyl ring could improve the binding interactions between Bcl-2 and diarylpentanoids, thus leading to better anti-cancer activity." (PMID 32858795, 2020).
cancer (continued). "To test this hypothesis using cancer cell lines identified in the present study to be less sensitive to fadraciclib, we determined the effects of fadraciclib combined with BCL2 inhibitor venetoclax (ABT-199), or BCL2/BCL2L1/BCL2L2 (bcl-w) inhibitors ABT-263 or ABT-737 in THP-1." (PMID 32645016, 2020). "Therefore, interference with BCL-2 expression is an effective strategy for treating cancer." (PMID 33150184, 2020). "Therefore, we hypothesized that DYRK1A suppression would sensitize cancer cells to Bcl-2 inhibitor treatment by suppressing Mcl-1 expression." (PMID 32587776, 2020). "A recent study outlined that Beclin-1 may interact also with members of the bcl-2 protein, acting as a tumor suppressor protein, and this finding could explain, at least partially, its positive prognostic role in different types of human cancers." (PMID 33330070, 2020). "BCL-1, myeloid-cell leukemia (MCL-1), and B-cell lymphoma extralarge (BCL-XL) are antiapoptotic BCL-2 proteins frequently overexpressed in human cancer and protect cells against apoptosis under normal conditions in breast, prostate, and cholangiocarcinoma cancer cells." (PMID 32411231, 2020). "Similarly, some authors demonstrated a reduction of Bcl-2 gene or protein expression in endothelial cells, human osteoblastic cells, and carcinoma cells." (PMID 33536932, 2020). "Several clinical studies demonstrated that the overexpression of the antiapoptotic BCL-2 protein is a negative prognostic marker in various tumours; while high Bax expression was associated with a better response to chemotherapy in many cancers forms." (PMID 31561546, 2019). "Two major pathways that are mutated in many cancers, are those involved in MHC-I expression and BCL-2 overexpression, paralleling observations in reservoir harboring cells: the HIV protein Nef downregulates MHC-I expression, while Tat can upregulate BCL-2 expression." (PMID 31447850, 2019). "Therefore, it is unsurprising that cancer cells show alteration in their Bcl-2 landscape." (PMID 31681471, 2019). "Therefore, we may speculate that a cancer cell needs to choose to deploy Bcl-2 for its canonical role at the mitochondria, preventing Bax/Bak activity, or an alternative function at the ER, inhibiting IP3R activity." (PMID 30718472, 2019). "Here, we propose an integration of approaches to shed light on the pro-survival Bcl-2 proteins, by bridging two of the major branches of bioinformatics: (i) analysis of high-throughput sequencing data, and (ii) molecular modeling to unveil cancer-related alterations." (PMID 31825969, 2019). "This equilibrium is affected by the expression level of the different BCL-2 proteins—indeed, one of the most often occurring chemo-resistance mechanism is ascribed to the overexpression of anti-apoptotic proteins in several types of cancer, for example in hematologic malignancies." (PMID 31159324, 2019). "Therefore, up-regulation of Bcl-2 by PRDM10 may be a potential mechanism for tumoriginesis in cancers overexpressing PRDM10." (PMID 31143550, 2019). "However, it is not only Bcl-2 which is aberrantly regulated in cancer." (PMID 31681471, 2019). "Furthermore, AURKA could inhibit the apoptosis of cancer cells by decreasing pro-apoptotic modulators (Caspase-3, Bax) and increasing anti-apoptotic regulators (Bcl-2)." (PMID 31706255, 2019).
cancer (continued). "Bcl-2 and Bax produce opposing effects in the regulation of cell apoptosis, and the proportion of Bcl-2 and Bax protein determines whether cells survive or undergo apoptosis, which in turn influences the therapeutic effects of different cancer treatments." (PMID 30578377, 2019). "Indeed, BCL-2 emerged as a valuable target to stimulate apoptosis in various cancer cells." (PMID 31450709, 2019). "We therefore hypothesized that the BCL2 variant is a determinant of paclitaxel resistance and that the phenomenon is not specific to a type of cancer." (PMID 31044156, 2019). "It’s reported that SATB1 might cooperatively regulate expression of the anti-apoptotic BCL2 and pro-apoptotic NOXA genes to participate in disruption of apoptosis, which is a hallmark of cancer that reinforces tumorigenesis and resistance to cytotoxic cancer therapies." (PMID 31130823, 2019). "Moreover, Choi and colleagues reported that açaí treatment down-regulated myeloperoxidase (MPO) and proinflammatory cytokines (TNF-α, IL-1β and IL-6), inhibited cyclooxygenase 2 (COX-2), PCNA and Bcl-2, and increased Bad and cleaved caspase-3 expression in an experimental model of cancer colon." (PMID 29966007, 2018). "Therefore, targeting Bcl-2 should sensitize ABC294640's anti-cancer efficiency." (PMID 29416779, 2018). "Therefore, using a pan-BCL-2 inhibitor strategy to treat the most aggressive types of cancer may have clinical benefit." (PMID 29077093, 2018). "It was previously reported that luteolin could decrease Bcl-2 expression in various cancer cells." (PMID 30454003, 2018). "In addition, AT-101 was shown to prevent the interaction between Bcl-2 and Beclin-1 at the endoplasmic reticulum, to decrease the levels of Bcl-2 and to increase Beclin-1 expression by inducing Beclin-1 Atg5-dependent autophagic pathway in cancer cells." (PMID 30459622, 2018). "Similarly, inhibition of Bcl‐2 also showed promising effects in various cancers including MPM." (PMID 29094504, 2018). "As an anti-apoptotic protein, the high-expression of Bcl-2 could impede apoptosis in cancer cells." (PMID 30002603, 2018). "It has been reported that DHA could induce apoptosis via modulating the cytochrome c release, Bax overexpression, increase in Bax/Bcl2 ratio, and activation of caspases 3, 8, and 934,36-38, and also there is no doubt that the induction of apoptosis is an effective strategy for cancer control." (PMID 30323180, 2018). "It has been suggested that the non-structural protein 5A (NS5A), encoded by HCV RNA genome, can decrease miR-503, which is abnormally expressed in various cancers and may play complicated and tissue-specific roles in cancer, and increase bcl-2 by inhibiting NF-κB activation." (PMID 29669594, 2018). "However, the inhibition of the PI3K/Akt/mTOR pathway by small-molecule PI3K inhibitors primes cancer cells to mitochondrial apoptosis by tipping the balance toward proapoptotic Bcl-2 proteins, resulting in increased mitochondrial outer membrane permeabilization." (PMID 28959140, 2017). "Similarly, in previous studies, Bcl2 upregulation has been reported in many types of cancer." (PMID 29104726, 2017). "Thus, targeting the Ca2+-modulating abilities of Bcl-2 proteins may offer novel anti-cancer strategies." (PMID 28516063, 2017). "Thus, BCL2 proteins are targetted by BCL2-inhibitors in cancer therapy to promote apoptosis." (PMID 28373964, 2017).
cancer (continued). "Furthermore, the different regulations of Bcl-2 mRNA at different time points may be due to the different mechanisms of compensation triggered by stress or adaptation signaling in cancer cells, such as epigenetic mechanisms." (PMID 28947928, 2017). "However, VDAC1 is also important in mitochondria-mediated apoptosis, mediating release of apoptotic proteins and interacting with anti-apoptotic proteins, such as B-cell lymphoma 2 (Bcl-2), Bcl-xL, and hexokinase (HK), which are also highly expressed in many cancers." (PMID 28824871, 2017). "High expression of Bcl-2 is associated with different cancer types, and has been reported in esophageal cancer, non-small cell lung cancer, endometrial cancer, breast cancer, prostate cancer, lung cancer, chronic lymphocytic leukemia, diffuse large B-cell lymphoma etc." (PMID 28445963, 2017). "Our results suggest that MA may serve as an autophagy activator by directly blocking the Bcl2-Beclin1 interaction to release free Beclin1 required for the recruitment of autophagy positive regulators, implying MA may exert its anti-cancer activity by regulating autophagy." (PMID 29088805, 2017). "Therefore, agents with inhibitory activities toward anti-apoptotic Bcl-2 members may be valuable to fight against cancers." (PMID 26931119, 2016). "Therefore we last asked whether this modified form would still be an eligible target for anti-neoplasic treatments that prove toxic for cancer cells because they trigger Bcl-2/Bcl-xLphosphorylation and hence abrogate their anti-apoptotic activity." (PMID 26958941, 2016). "Previous studies showed that MALAT-1 promotes cancer progression, mainly through the regulation of gene expression, for example, the epithelial mesenchymal transition associated genes, ZEB1, ZEB2, and Slug and the apoptosis related genes, CASP3, CASP8, BAX, BCL2, and BCL2L1." (PMID 26989678, 2016). "Besides Bcl-2, other members of the apoptotic pathways, such as Bcl-XL have been found to be oncogenic drivers in colorectal cancer, while Bax, yet another member, has been inactivated in some other cancers, such as colon cancer and hematopoietic malignancies." (PMID 28025559, 2016). "Therefore, it is possible that Bcl-2 may contribute to cancer cell invasion and metastasis by targeting COX." (PMID 26621844, 2016). "However, there are some cancers that cannot be treated with these Bcl-2 inhibitors, in which the upregulation of Mcl-1 may play a key role." (PMID 26056043, 2015). "As a result, there are numerous newly designed and synthesized chemotherapeutic agents targeting the BH-3 domains of anti-apoptotic Bcl-2 members to induce apoptosis and inhibit the function of Bcl-2/Bcl-xL proteins, which may be useful in the management and treatment of cancers." (PMID 25672487, 2015). "Thus, the bcl-2 targeting may be a strategy of choice to improve treatment efficacy and overcome drug resistance to cancer chemotherapy." (PMID 26535028, 2015). "Thus, targeting of Bcl-2 may be a strategy of choice to improve treatment efficacy and overcome drug resistance to cancer chemotherapy." (PMID 26535028, 2015). "In an unbiased screen of 242 genomically characterized cancer cell lines with an Informer Set of 354 small molecules, cell lines with β-catenin mutation were reported to be amongst the most sensitive to navitoclax (ABT-263), an inhibitor of BCL-2, BCL-XL and BCL-W." (PMID 26134786, 2015). "However, in other cancer cells, melatonin induces a decrease in BCL-2." (PMID 26025920, 2015). "Therefore, it is reasonable to speculate that the regulation of bcl-2 in hyperoxic lung may be different from that in cancer cells." (PMID 25938838, 2015). "Therefore, inhibition of Bcl2 expression contributes to cancer therapy." (PMID 26556865, 2015).